MDK (midkine)
Diseases named in the same sentence as MDK in open-access papers (continued):
Sharing a sentence is not in itself a finding about the gene and the disease.
cancer (continued). "In addition to MDK protein, high expression of MDK mRNA may also predict worse OS in patients with cancers, but the studies were fewer." (PMID 29872508, 2018). "Therefore, the inhibition of MDK is considered a potential strategy for cancer therapy." (PMID 23976985, 2013). "However, only the concentrations of VEGF, and leptin but not midkine, are associated with weight loss in the examined cohort of cancer patients." (PMID 20920199, 2010). "Afterwards, the impact of MDK on the Wnt/β‐catenin signalling pathway and EMT markers in cancer cells was confirmed using Western blot analysis." (PMID 40468625, 2025). "Inhibiting MDK following treatment with IFN-γ reduced both the expression of EMT markers like Snail and vimentin and reduced the migration and invasion of various cancer lines." (PMID 40429950, 2025). "Midkine (MDK), a heparin-binding growth factor, activates multiple key pathways such as MAPK, WNT, and TGF-β, leading to increased cancer proliferation, angiogenesis, and metastasis." (PMID 40269686, 2025). "Within MDK signaling, MDK-NCL and MDK-ITGB1 interactions were predicted as predominant between ABS cancer cells and Tfh cells." (PMID 39649843, 2025). "Both MDK and NCL exhibited significantly high expression across multiple cancer types, with their expression levels in GC tissues notably higher than in normal gastric tissues." (PMID 41249133, 2025). "PTPRZ1 is activated by MDK, fueling cancer via the PI3K pathway, and blocking PTPRZ1 stopped cancer cell growth and spread, revealing PTPRZ1‐MDK as a new treatment target for LUSC." (PMID 40899632, 2025). "Another receptor on the cell membrane of CAFs, MDK, interacts with NCL/SDC2/SDC on cancer cells, potentially serving as therapeutic targets." (PMID 38720108, 2024). "Silence of miR-1275 leads to upregulation of MDK and further activating PI3K/AKT signaling to enhance the properties of cancer stem cells and promote chemoresistance(.Han, Li, Xu, Fu, Wang, Wang, Xia, Wang and Ma 2023)." (PMID 39014225, 2024). "Midkine is a cancer biomarker; PPS shows potential as an MDK cancer therapeutic, and targeting MDK abrogates IFN-γ-elicited metastasis in a number of cancer types." (PMID 36986536, 2023). "Based on our results, MDK, which was secreted by GBM cancer cells, induced the migration and immunosuppressive polarization of macrophages." (PMID 35558067, 2022). "Our results clarify that MDK promotes cancer cell proliferation by suppressing the LKB1-AMPK axis, and MDK expression correlates with clinical outcomes and inversely correlates with LKB1/AMPK signaling pathway activation." (PMID 35487917, 2022). "Cell-cell communication indicated that endocrine cells had impacts on cancer cells through strong MDK-SDC4 and MDK-NCL interactions, while endothelial cells affected tumor cells mainly through COL4A2-SDC4 and COL4A1-SDC4 interactions." (PMID 35898512, 2022). "Thus, intra-tumoral heterogeneity, which is believed to underlie therapy resistance in many malignant tumors, also occurs in mTORC1-hyperactive AML and LAM, and combinatorial targeting mTORC1 and factors such as MDK that contribute to this heterogeneity may enhance the efficacy of mTORC1 inhibition." (PMID 36028490, 2022). "To further validate the IFN-γ-MDK regulatory axis, we treated the HCT116 cancer cell line with different concentrations of IFN-γ and verified that activation of MDK by IFN-γ was dose-dependent at both the mRNA and protein levels." (PMID 35747815, 2022). "We also noticed that growth factors, including NOV, BMP4, MDK, GDF15, VEGFC, NTF3, and LIF, were previously reported to promote cancer development, especially in cancer metastasis in various cancers, including CRC." (PMID 34440086, 2021). "In oral squamous cell carcinoma, midkine, a member of the heparin-binding growth factor family, was shown to mediate CAF-induced cisplatin resistance in cancer cells." (PMID 33050576, 2020).
cancer (continued). "And most of the 24 DEPs (CDK1, SFN, PRKAR2B, MKI67 and MDK involved in the cell cycle; LOXL2, P4HA1, P4HA2, SPRX, DES, PRPH and CALML3 involved in construction and regulation of extracellular matrix; IL33 and EHD3 may involve in immune) were linked to cancer hallmarks." (PMID 33200655, 2020). "Midkine (MDK) is a heparin-binding cytokine most notably known for its role in embryonic development and cancer through promoting cell migration, survival, proliferation and angiogenesis." (PMID 32879333, 2020). "In contrast to MDK, expression of AGR2 is induced by androgens and was found to be inversely correlated to cancer-specific survival." (PMID 31877738, 2019). "It is also notable that we identified over 10 cancer-related genes (including PHGDH, CCND1, IGFBP-2, XAGE1B/E, CYP4F22, RBM11, ORAOV1, MDK, UGT3A5, SSX5, FBL, NKX2) potentially overexpressed in EFT tumors." (PMID 30093970, 2018). "ALK is activated by its ligands, midkine (MDK) and pleiotrophin (PTN), both of which serve as mitogenic and angiogenic factors in cancer." (PMID 24163262, 2013). "Although the involvement of midkine in inflammation is well-documented, only a weak correlation between midkine and CRP in cancer patients has been reported." (PMID 20920199, 2010). "Additionally, MDK triggers NOTCH1 and NOTCH2 signaling, pathways known to promote EMT and chemoresistance in multiple cancer types." (PMID 40500394, 2025). "It has been reported that MDK interacts with the ITGA4 and ITGA6 receptors, activating a series of downstream signaling cascades that significantly enhance cancer cell growth, migration, metastasis, and angiogenesis, thereby further exacerbating the progression of HCC." (PMID 40333631, 2025). "Additionally, targeting MDK has been shown to eliminate IFN-γ-induced metastasis in various cancer types, further highlighting its potential role in cancer progression and metastasis." (PMID 40777026, 2025). "Additionally, the receptor–ligand interaction analysis revealed that in the MDK-NCL signaling network, cancer.cell. displayed increased communication with CD8_ANXA1, Mono_EREG, and CAF_C3 in the post-NACT group." (PMID 40725006, 2025). "MDK is a heparin-binding growth factor and has been reported to promote EMT in cancer cells." (PMID 38416732, 2024). "Limited research explored the relationship between MDK and RAS in cancers." (PMID 37743493, 2023). "Midkine expression is enhanced in several cancers, whereas its expression in non-malignant cells is relatively limited." (PMID 37367056, 2023). "Taken together, EC cancer cells may shape TME by inhibiting immune cells and “educating” stromal cells via MDK-NCL signal." (PMID 37081869, 2023). "Collectively, these data identify an IFN-γ responsive protein, MDK, in counteracting anti-proliferation while endowing the pro-metastatic role of IFN-γ in cancer treatment, and we therefore propose the combined utilization of the MDK inhibitor in IFN-γ-based therapies in future OC treatment." (PMID 36672515, 2022). "Midkine is also interesting as a possible therapeutic target; not only is midkine considered a prognostic indicator for various cancers, but it has also garnered attention as a therapeutic target." (PMID 36016386, 2022). "MDK is a heparin-binding growth factor well-documented to promote EMT and cancer metastasis." (PMID 35747815, 2022). "Indeed, we validated that MDK overexpression led to EMT and metastasis in all five cancer cell lines." (PMID 35747815, 2022). "Our data indicated that iMDK application could globally eliminate IFN-γ-induced MDK, reverse IFN-γ-induced EMT activation, and ultimately abrogate IFN-γ-triggered cancer migration and invasion in all examined cancer cell lines." (PMID 35747815, 2022). "To verify this hypothesis, we treated different cancer cell lines with IFN-γ (50 ng/ml) and then examined the alterations of MDK expression in the mRNA and protein levels." (PMID 35747815, 2022).
cancer (continued). "MDK was relevant as it is overexpressed in a broad variety of cancer types, and no pharmacological agents have been described to block its expression." (PMID 34762341, 2021). "Heatmap of differential gene expression in GGN-ADC and SADC showed that some cancer-promoting genes, such as HSPB1, CCL2, CXCL14, MDK, and MMP7, were highly expressed in SADC, indicating that the cancer cells derived from SADC had a higher malignant degree than those derived from GGN-ADC." (PMID 33083004, 2020). "In addition, MDK secreted from NSCLC cells interacted with Notch2 which activated the Notch signaling pathway and induced EMT, upregulated NF-κB, and increased cancer promotion." (PMID 32847073, 2020). "Consistent with the serum analysis, the urine midkine levels were significantly increased in patients with NSCLC compared with cancer-free individuals (0.01<P<0.05, data not shown)." (PMID 27974680, 2016). "Since the truncated midkine has been found in cancerous colorectal tissue and in metastatic lymph nodes, but not in adjacent noncancerous tissue, the cancer-specific nature of the truncated form has been suggested." (PMID 22562257, 2012). "They found elevated MDK protein expression in all HCC cell lines compared with controls, while IHC analysis in the TMA exhibited high MDK expression in the form of diffused cytoplasmic staining in 72% of HCCs compared with normal adjacent liver tissue or cancer-free cirrhotic samples." (PMID 38247828, 2024). "Notably, we identified several key ligand-receptor pairs in TNChigh cancer cells and immune cells, including NECTIN2-TIGIT, MIF-(CD74+CD44), MDK-NCL, LAMB3-CD44, COL1A2-CD44, COL1A1-CD44, CD99-CD99, APP-CD74, and GZMB-PARD3 were identified in TNChigh cancer cells and immune cells." (PMID 38711034, 2024). "Collectively, our data identify a novel IFN-γ-STAT1-MDK signalling axis, which confers the pro-metastatic adverse effect of IFN-γ in immunotherapy, whereas targeting MDK may efficiently abrogate IFN-γ-elicited cancer metastasis." (PMID 35747815, 2022). "Midkine (MDK) is a heparin-binding growth factor with multiple functions, including anti-apoptotic, migratory ion-promoting, angiogenic, and antimicrobial effects and is strongly expressed during embryogenesis and most malignant tumors, but in normal adult tissues, it is weak or undetectable." (PMID 32923383, 2020). "Although midkine (MK) is a prognostic biomarker for several known cancers, it is not known whether it can be used as such in resectable CHCC-CC." (PMID 29486735, 2018). "However, no medication was available to block MDK expression directly in cancer patients." (PMID 37743493, 2023). "To test this in vitro, we treated cancer-cell suspension from tumors of three patients (HN372, HN377, HN380) with or without MDK inhibitor." (PMID 36973261, 2023). "Genes coding for proteins supporting cancer cells survival or proliferation such as FOXD1 or EIF5A appeared up-regulated in resistant and not in sensitive, while E-cadherin, CLDN7, MDK, PKDCC, and JAG1 were more down-regulated." (PMID 27835869, 2016). "To test whether MDK inhibition would attenuate IFN-γ-induced metastasis, we added iMDK (100 nM) to the IFN-γ-treated cancer cells, which resulted in no conspicuous cell death under microscope." (PMID 35747815, 2022).
cardiovascular diseases (4 papers, 2014 to 2023). "In recent years, MDK has also been implicated in various cardiovascular diseases." (PMID 37484982, 2023). "Increased levels of MDK have been proposed as a therapeutic target for different cardiovascular diseases." (PMID 28920060, 2017). "Therefore, MDK is considered a possible therapeutic target in cardiovascular diseases." (PMID 28920060, 2017). "The role of MDK is not clear in cardiovascular disease and currently there is no consensus if it plays a beneficial or detrimental role in HF." (PMID 28920060, 2017). "However, there is still no consensus on whether MDK is beneficial or detrimental to cardiovascular diseases (extensively discussed by our group)." (PMID 37484982, 2023).
infection (4 papers, 2012 to 2023). The state of being infected such as from the introduction of a foreign agent such as serum, vaccine, antigenic substance or organism. "Mice inoculated with six viruses, including CK/VN/1180/06, DK/VN/31/07, DK/VN/34/07, DK/VN/43/07, CK/VN/45/07, and MDK/VN/46/07, lost over 20% of their body weight and died within 10 days of infection." (PMID 23226433, 2012).
kidney disease (4 papers, 2018 to 2023). "Changes in systemic midkine levels i.e., increased circulating midkine, could be a prognostic indicator of potentially worsening kidney disease." (PMID 35846341, 2022). "This pilot-study identified several serum biomarkers that could be used to predict progression of T2D to more serious kidney disease: namely, midkine, sTNFR1 and 2, H-FABP and Cystatin C. Our results warrant confirmation in a longitudinal study using a larger patient cohort." (PMID 35846341, 2022). "Midkine (MDK), a heparin-binding growth factor cytokine, is involved in the pathogenesis of kidney diseases by augmenting leukocyte trafficking and activation." (PMID 32879333, 2020). "Further studies are required to confirm the relationship between MDK and longitudinal renal function and CKD outcomes in populations with prevalent kidney disease." (PMID 32879333, 2020). "Our findings may argue that MDK is not an early biomarker in chronic and age-related renal function changes and kidney disease outcomes, which is supported by both experimental and clinical evidence on the involvement of MDK in acute inflammation and kidney injury." (PMID 32879333, 2020). "There has not been investigation of MDK or FSTL3 in other subset of SSc patients who might have increased concentrations of those specific proteins, such as patients with cardiac involvement or renal disease." (PMID 30115106, 2018).
neurodegenerative disease (4 papers, 2021 to 2025). A disorder of the central nervous system characterized by gradual and progressive loss of neural tissue and neurologic function. "Finally, a recent has described MDK levels in the cerebrospinal fluid of Parkinson’s disease (PD) patients as a supportive diagnostic biomarker, highlighting its potential for other neurodegenerative disease such as MS or AD." (PMID 38098484, 2023). "Although previous literature has suggested MDK as a candidate therapeutic target in neurodegenerative disease contexts, our specific findings require disease-specific validation." (PMID 41318503, 2025). "Similarly, assessing and importantly inhibiting MDK expression may also be of relevance in the context of proinflammatory roles of this protein in autoimmune and degenerative diseases." (PMID 34762341, 2021).
inflammation (2 papers, 2017 to 2025). Aberrant reaction of the microcirculation characterized by movement of fluid and leukocytes from the blood into extravascular tissues. "For further evaluation of the role of MDK in pulmonary inflammation, we analyzed the effect of MDK knockdown on LPS-induced inflammatory cytokine expression in bronchial epithelial cells." (PMID 40943439, 2025). "To determine the role of MDK in acute lung inflammation, we used an LPS-induced pulmonary inflammation model." (PMID 40943439, 2025). "Further study is required to fully elucidate the role of MDK in acute lung inflammation." (PMID 40943439, 2025). "Because lung epithelial cells play important roles in pulmonary inflammation, we used BEAS-2B human bronchial cells to analyze the role of MDK in LPS-induced pulmonary inflammation." (PMID 40943439, 2025).
neurological disorders (2 papers, 2023 to 2024). "MDK is highly expressed during embryogenesis, and it has been involved in inflammation and neurological disorders." (PMID 39300217, 2024). "Finally, we highlight the therapeutic potential of MDK and discuss potential therapeutic approaches for the treatment of neurological disorders." (PMID 38098484, 2023).
cardiac disease (1 paper, 2017). "This review focuses on what is known about the effect of exogenous versus myocardial MDK in various cardiac disease models in an effort to better clarify the role of midkine in HF." (PMID 28920060, 2017). "In certain models of cardiac disease, increased MDK levels appear to impart benefits such as survival and enhanced angiogenesis, whereas in others, upregulated MDK seems to exacerbate cardiac remodeling and dysfunction." (PMID 28920060, 2017).
kidney (1 paper, 2026). "However, Western blot results demonstrated a gradual increase in MDK protein expression in hippocampal tissue on the 1st, 7th, and 28th days following kidney injury." (PMID 41276912, 2026).
MDK also shares sentences with these, for which no sentence is quoted: astrocytoma (5 papers); thyroid cancer (3); cutaneous melanoma (2); idiopathic pulmonary fibrosis (2); inflammatory bowel disease (2); kidney cancer (2); malignant mesothelioma (2); papillary thyroid cancer (2); systemic lupus erythematosus (2); ulcerative colitis (2); adenocarcinoma (1); adenoma (1); ameloblastoma (1); amyotrophic lateral sclerosis (1); anaplastic astrocytoma (1); anorexia nervosa (1); Autoimmunity (1); benign gynecological tumors (1); benign tumors (1); biliary tract cancer (1); brain cancer (1); carotid atherosclerosis (1); Chronic Obstructive Lung Disease (1); cognitive disorder (1); coronary artery calcification (1); crescentic glomerulonephritis (1); deep vein thrombosis (1); diabetes (1); ductal carcinoma in-situ (1); emphysema (1).
A further 36 diseases each share a sentence with MDK in 1 paper.